THOC7 (THO complex subunit 7)
Description:
Component of the THO subcomplex of the TREX complex which is thought to couple mRNA transcription, processing and nuclear export, and which specifically associates with spliced mRNA and not with unspliced pre-mRNA. Required for efficient export of polyadenylated RNA. Plays a key structural role in the oligomerization of the THO-DDX39B complex. TREX is recruited to spliced mRNAs by a transcription-independent mechanism, binds to mRNA upstream of the exon-junction complex (EJC) and is recruited in a splicing- and cap-dependent manner to a region near the 5' end of the mRNA where it functions in mRNA export to the cytoplasm via the TAP/NXF1 pathway. (Microbial infection) The TREX complex is essential for the export of Kaposi's sarcoma-associated herpesvirus (KSHV) intronless mRNAs and infectious virus production.
Synonyms: fSAP24; NIF3L1BP1; FLJ23445; hTREX30
Tractability: PROTAC: ubiquitination databases record sites on it; its protein half-life has been measured.
Gene: Protein-coding gene on chromosome 3 (63,833,870 to 63,863,868, reverse strand). Ensembl gene ENSG00000163634.
Subcellular location: Cytoplasm; Nucleus; Nucleus speckle
Subcellular location (Human Protein Atlas): Cytosol; Nuclear speckles
Pathways (Reactome):
Metabolism of RNA: Transport of Mature mRNA derived from an Intron-Containing Transcript; mRNA 3'-end processing
Gene Ontology:
Molecular function: protein binding
Biological process: mRNA export from nucleus; mRNA processing
Cellular component: chromosome, telomeric region; cytoplasm; cytosol; nuclear speck; nucleus; THO complex; THO complex part of transcription export complex; transcription export complex; nucleoplasm
Genetic constraint (gnomAD): Loss-of-function variants: 18 observed, 30.75 expected, observed/expected ratio (o/e) 0.59, 90% interval 0.4 to 0.87. The upper end of that interval is the gene's LOEUF score, 0.87, which puts it in group 3 of 6, group 1 being the genes least tolerant of losing a copy. Missense variants: 170 observed, 222.78 expected, observed/expected ratio (o/e) 0.76, 90% interval 0.67 to 0.87. Synonymous variants: 73 observed, 73.95 expected, observed/expected ratio (o/e) 0.99, 90% interval 0.82 to 1.2.
Homologues: Orthologues: chimpanzee THOC7 (100% identical), macaque THOC7 (99% identical), dog THOC7 (99% identical), guinea pig THOC7 (99% identical), mouse Thoc7 (98% identical), pig THOC7 (97% identical), rat Thoc7 (96% identical), tropical clawed frog thoc7 (84% identical), zebrafish thoc7 (75% identical), Drosophila melanogaster thoc7 (40% identical), Caenorhabditis elegans thoc-7 (28% identical).
Diseases named in the same sentence as THOC7 in open-access papers:
THOC7 is named in the same sentence as 9 diseases in open-access papers, as found by Europe PMC text mining. Sharing a sentence is not in itself a finding about the gene and the disease. The quoted sentences say what the papers report.
breast carcinoma (1 paper, 2011). "We evaluated the expression of the components of the human THO complex, THOC1, THOC2, THOC3, THOC5, THOC6 and THOC7, as well as the expression levels of UAP56 and ALY in breast cancer cell lines." (PMID 21329510, 2011).
cervical cancer (1 paper, 2021). A primary or metastatic malignant neoplasm involving the cervix. "Studies have shown a relationship between the downregulation of THOC7 and the activation of tumorigenic pathways in cervical cancer." (PMID 35126467, 2021).
virus infection (1 paper, 2019). "Additionally, we examined the effect in the presence and absence of THOC7 in MCF7 cells and found a weak downregulation of TBK1 by THOC7 expression, but obvious effect upon virus infection." (PMID 30769920, 2019). "THOC7 interacted with MAVS, TBK1, IKKε, and IRF3 and, notably, the interaction was decreased with MAVS, but increased with TBK1 after virus infection, indicating that THOC7 have a significant function by targeting TBK1 in the antiviral response." (PMID 30769920, 2019). "THOC7 interacted with TBK1 and was increased after viral infection." (PMID 30769920, 2019).
cancer (1 paper, 2020). A tumor composed of atypical neoplastic, often pleomorphic cells that invade other tissues. "Multiple TREX mRNA export complex subunits (e.g., THOC1, THOC2, THOC5, THOC6, THOC7) have now been implicated in neurodevelopmental disorders (NDDs), neurodegeneration and cancer." (PMID 32116545, 2020).
THOC7 also shares sentences with these, for which no sentence is quoted: schizophrenia (2 papers); infection (1); lung adenocarcinoma (1); neurodevelopmental disorder (1); pancreatic tumors (1).